MPO (myeloperoxidase)
Diseases named in the same sentence as MPO in open-access papers (continued):
Sharing a sentence is not in itself a finding about the gene and the disease.
metabolic syndrome (continued). "In metabolic syndrome patients, chair‐side testing for biomarkers such as aMMP‐8 and MPO may facilitate earlier preventive detection and monitoring of periodontal disease progression." (PMID 38852177, 2025). "Markers of intestinal permeability and inflammation measured in urine (lactulose, mannitol) and stool (myeloperoxidase, protozoal infections) during infancy may predict metabolic syndrome in adulthood." (PMID 36096405, 2022). "Besides, the induction of dyslipidemia with hypercholesterolemic diet (HC) promoted a significant increase in plasma MPO (p < 0.05) when compared with NC." (PMID 30781884, 2019). "In this sense, the findings of this study suggest the protective effect of the LRE on a dyslipidemia model evidenced by the decrease in plasma levels of triglyceride and malondialdehyde, as well as the reduction of plasma myeloperoxidase activity and liver steatosis." (PMID 30781884, 2019). "Metabolic syndrome components may thus impact increased salivary MPO levels." (PMID 38852177, 2025). "Interestingly, both Fibrinogen and MPO were associated with DLCO and FEV1 when all patients were considered regardless of metabolic syndrome, suggesting that in the general population these associations may be driven by stronger associations within the non-metabolic syndrome subpopulation." (PMID 22701684, 2012). "NGAL and MPO, both neutrophil associated markers, were also significantly associated with FEV1/FVC ratio in patients without metabolic syndrome." (PMID 22701684, 2012). "While the p value for interaction with metabolic syndrome was not significant at the p<0.05 level for any of these analytes, interaction p values for MPO and Fibrinogen were 0.09 and 0.08, respectively." (PMID 22701684, 2012). "In another study, TNF-α and IL-6 concentrations and myeloperoxidase activity were higher (whereas catalase and superoxide dismutase activities were lower) in consumers with a high intake of ultra-processed food (UPF) with metabolic syndrome than in those with a low intake of UPF." (PMID 38542788, 2024). "Mathew identified that lifestyle changes could enhance HDL function via suppressing oxidation by myeloperoxidase without changes on the proteomic composition in subjects with metabolic syndrome." (PMID 37386457, 2023). "The results demonstrated that age, dyslipidemia, atrial fibrillation, triglyceride, MR (grades 2 to 4), mean TLR2+/CD14+ cells, TLR2+/CD14+ cells <25%, TLR4+/CD14+ cells <0.25%, mean MPO+/CD14+cells, MPO+CD14+ cells <20%, sST2 <14,000 (pg/mL), and mean sST2 were significantly predictive of mild CCS." (PMID 32054047, 2020). "When subjects were sub-grouped based on the presence of coexisting metabolic syndrome, we observed that MPO and Fibrinogen were strongly negatively associated with FEV1/FVC and DLCO, respectively, in patients without metabolic syndrome but not in patients with metabolic syndrome." (PMID 22701684, 2012).
psoriasis (37 papers, 2013 to 2026). An autoimmune condition characterized by red, well-delineated plaques with silvery scales that are usually on the extensor surfaces and scalp. "This heightened MPO activity can lead to tissue damage and exacerbate the inflammatory processes underlying psoriasis." (PMID 39456475, 2024). "Specifically, MPO was a marker of neutrophils, and a typical histopathological hallmark of psoriasis was the abundance of the neutrophils in the psoriatic skin lesions." (PMID 34641629, 2021). "Given that MPO serves as a biomarker for the activation of neutrophils and monocytes, the oxidative stress caused by elevated MPO can worsen mitochondrial dysfunction, thereby contributing to the psoriasis etiopathogenesis." (PMID 39456475, 2024). "Extracellular traps from both neutrophils and mast cells have been demonstrated in psoriatic skin lesions and from purified neutrophils from psoriasis patients in association with IL-17 and MPO, directly implicating extracellular traps in the pathogenesis of disease." (PMID 23514610, 2013). "In addition, serum myeloperoxidase (MPO) level is elevated in psoriasis and may be a biomarker for cardiovascular risk." (PMID 29065479, 2017). "Significantly higher circulating neutrophils (p < 0.001) and levels of NET-associated markers (i.e., MPO-DNA complex, CitH3, PAD4, NADPH oxidase, and NE) were observed in active psoriasis patients compared to controls." (PMID 41596128, 2026). "Our analyses of psoriasis skin biopsies and circulating MPO–DNA complexes are in agreement with these reports." (PMID 40270954, 2025). "In this study, we provide evidence that both cit-LL37 and carb-LL37 are present in the psoriasis lesional skin, at skin sites where neutrophils are present, as shown by the presence of MPO staining in the psoriasis skin biopsies." (PMID 40270954, 2025). "NET structures were detectable in the psoriasis dermis, where structures similar to DNA filaments decorated by MPO or modified LL37 were observed." (PMID 40270954, 2025). "Myeloperoxidase inhibition attenuates psoriasis severity in murine models when administered either systemically or topically." (PMID 40332377, 2025). "A study on children with psoriasis showed that they had significantly higher MPO levels and activity than healthy controls." (PMID 39456475, 2024). "This review explores oxidative stress biomarkers and parameters in psoriasis, including myeloperoxidase, paraoxonase, sirtuins, superoxide dismutase, catalase, malondialdehyde, oxidative stress index, total oxidant status, and total antioxidant status." (PMID 39456475, 2024). "Tracking MPO activity and levels provides insights into the extent of oxidative stress and inflammation in psoriasis, serving as potential biomarkers for disease severity and progression." (PMID 39456475, 2024). "In the group of patients with mild psoriasis, there were positive correlations between DNase I and NE-DNA (r = 0.6016, p < 0.05), MPO-DNA and NE-DNA (r = 0.5297, p < 0.05), as well as citH3 and MPO-DNA (r = 0.5679, p < 0.05)." (PMID 39409000, 2024). "The identification of MPO gene mutations in patients with GPP further highlights the significance of MPO in psoriasis pathogenesis, offering potential avenues for targeted therapeutic interventions to mitigate inflammation and oxidative damage." (PMID 39456475, 2024). "To explore the function of keratinocyte GSDME in responses to psoriasis-like immune microenvironment, we first detected infiltration and activation of neutrophils by staining Ly6G and MPO in situ." (PMID 38429278, 2024). "Targeting MPO expression or activity presents a potential therapeutic approach to mitigate inflammation and oxidative damage in psoriasis and other inflammatory conditions." (PMID 39456475, 2024). "In conclusion, MPO plays a significant role in oxidative stress, inflammation, and tissue destruction in psoriasis-affected skin lesions, contributing significantly to the disease’s pathogenesis." (PMID 39456475, 2024).
psoriasis (continued). "In this study, the level of MPO–DNA complex was markedly elevated in serum samples from patients with PsA and psoriasis and further shown to positively correlate with psoriatic disease burden." (PMID 38802975, 2024). "Excessive or dysregulated MPO activity can lead to tissue damage and contribute to the pathogenesis of various inflammatory conditions, including autoimmune diseases like psoriasis." (PMID 39456475, 2024). "The results showed the elevated levels of NE-DNA, MPO-DNA, citH3, and DNase I in the patients with psoriasis compared to healthy volunteers (p < 0.05)." (PMID 39409000, 2024). "MPO-derived ROS contribute to oxidative damage to lipids, proteins, and DNA, crucial steps in psoriasis pathogenesis that perpetuate inflammatory processes." (PMID 39456475, 2024). "They discovered that administering MPO inhibitors, both through the bloodstream and directly to the affected area, resulted in a decrease in psoriasis severity." (PMID 39456475, 2024). "Elevated MPO levels have been observed in psoriasis-related skin lesions, indicating heightened inflammation and neutrophil activation." (PMID 39456475, 2024). "Research has shown that neutrophils from psoriasis patients have higher MPO and NOX2 activity, leading to increased ROS release compared with neutrophils from healthy individuals." (PMID 39148738, 2024). "A study conducted observed that the MPO levels were greater in psoriasis patients’ serum and skin compared to controls." (PMID 39456475, 2024). "In turn, a significantly increased level of DNAse I together with evaluated concentrations of citH3 and the MPO-DNA complex were noted in moderate and severe psoriasis." (PMID 39409000, 2024). "Noteworthy biomarkers such as myeloperoxidase (MPO), paraoxonase (PON), sirtuins (SIRTs), superoxide dismutase (SOD), and catalase (CAT) are emerging as key indicators of psoriasis pathogenesis and their association with mitochondrial ROS." (PMID 39456475, 2024). "To evaluate neutrophil infiltration into IMQ-induced psoriasis-like skin lesions, we performed immunostaining for myeloperoxidase (MPO)." (PMID 37717073, 2023). "The study revealed increased serum MPO–DNA complex in patients with psoriasis and its correlation with PsA disease activity." (PMID 35774788, 2022). "Serum myeloperoxidase–DNA (MPO-DNA) complex was detected by a modified enzyme-linked immunosorbent assay and compared among 74 patients with PsA, 58 patients with psoriasis (PsO), and 20 healthy controls." (PMID 35774788, 2022). "We found that myeloperoxidase inhibition ameliorated psoriasis severity when administered either systemically or topically." (PMID 34572970, 2021). "AWE also ameliorated skin lesions in IMQ-induced psoriasis-like skin inflammation and inhibited neutrophil infiltration, MPO release, ROS-induced damage, and skin proliferation." (PMID 34955833, 2021). "Since MPO is one of the important markers of NETosis, higher concentration in supernatants of neutrophils obtained from psoriasis patients and in LPS-treated cells suggests an increased NETosis in these groups." (PMID 32947961, 2020). "Our research confirms this previous observation, as elevated levels of NADPH oxidase and MPO are observed in the neutrophils of psoriasis patients, especially when activated by LPS." (PMID 32947961, 2020). "Higher levels of MPO in plasma and cell supernatants after incubation indicate that psoriasis leads to over-activation of neutrophils and oxidative stress, as reported in our previous work, resulting in an intensification of NETosis." (PMID 32947961, 2020). "In psoriasis, MPO is significantly increased in skin plaques and is positively correlated with the severity of psoriasis." (PMID 31649677, 2019). "Neutrophils obtained from patients with psoriasis were shown to possess increased MPO and NOX2 activities, and release more ROS compared with neutrophils from healthy individuals." (PMID 31649677, 2019).
psoriasis (continued). "Furthermore, in the psoriatic regional skin of mPGES-1−/− mice, there is a rapid and abundant accumulation of CD45-positive leukocytes on day 3 after psoriasis induction, correlating with the high MPO activity, an indicator of neutrophil infiltration." (PMID 40481552, 2025). "Cit-LL37 and carb-LL37 were detectable in the lesional psoriasis skin in the presence of MPO expression, suggesting that proteins released by neutrophils could be responsible for both PTMs." (PMID 40270954, 2025). "Interestingly, in our study, a positive correlation was also found between MPO-DNA and NE-DNA, but only in the group of psoriatic patients with a mild form of psoriasis." (PMID 39409000, 2024). "The main indices assessed were total oxidative status, reactive oxygen species, myeloperoxidase, ischemia modified albumin, advanced glycation end-products and advanced oxidation protein products whose values were higher in subjects with psoriasis versus their healthy counterparts." (PMID 35204165, 2022). "Notably, in patients with psoriasis, MPO is also increased in both psoriasis skin lesions and in the blood." (PMID 34639156, 2021). "Therefore, an increment in MPO levels marks well with neutrophil infiltration in the psoriatic lesions, with a positive correlation with psoriasis severity." (PMID 31991752, 2020). "Moreover, we observe that both the percentage of cells undergoing NETosis and MPO levels correlates with the severity of psoriasis, estimated by the PASI index and these correlations are observed in the case of stimulated and unstimulated cells." (PMID 32947961, 2020). "Importantly, the correlation with resistin, myeloperoxidase, and the effect of psoriasis treatment on the studied parameters is preliminary and was performed on a significantly smaller cohort than the other analyses." (PMID 31936662, 2020). "In addition, to evaluate NET formation in IMQ-induced psoriasis-like lesions, immunofluorescent co-staining for MPO and citrullinated histone H3 was performed." (PMID 33214582, 2020). "Serum MPO is also increased in patients with psoriasis, which may be related to recruited leukocytes in psoriatic skin lesions." (PMID 31649677, 2019). "Thus, the inhibition of neutrophils degranulation process or some of the enzymes contributing to psoriasis (NE, MPO, proteinase 3) are feasible targets for alleviating psoriatic symptoms." (PMID 31649677, 2019). "Therefore, we explored the presence of NETs in psoriasis patients by quantification of circulating MPO-DNA complexes, which showed significant increase in serum of psoriasis patients compared to healthy individuals." (PMID 31024570, 2019). "As a result, the myeloperoxidase inhibitor could serve as a potential medication for psoriasis." (PMID 40332377, 2025). "Thus, resistin, which is elevated in a minority of patients with moderate-severe psoriasis, may be more linked to mechanisms associated with RDW elevation than MPO, which may simply reflect skin release." (PMID 31936662, 2020). "Proteases released in the degranulation step by neutrophils, such as myeloperoxidase (MPO), neutrophil elastase (NE), proteinase 3, and cathepsin G, participate in the generation of ROS, proteolytical activation of inflammatory mediators, and formation of autoantigens in psoriasis." (PMID 31649677, 2019). "Therefore, the reduced level of DNase I, observed in the group of patients with mild psoriasis, may be related to the activity of inhibitors and/or insufficient stimulation by NETs (reduced levels of NE-DNA and physiological levels of MPO-DNA and citrullinated histones)." (PMID 39409000, 2024). "CD was found to decrease the serum levels of psoriasis-related inflammation mediators (i.e., TNF-α, IgG2a, and MPO)." (PMID 34641629, 2021). "PRM validation of 9 proteins that were highly expressed in the drug metabolism pathway further confirmed significant upregulation of MPO (17.05), TYMP (2.44), and IMPDH2 (1.78) in psoriasis lesions." (PMID 32817748, 2020).
psoriasis (continued). "Collectively, increased MPO-positive neutrophil infiltration and NET formation in Il36rn−/− mice would play a central role in the pathogenesis of IMQ-induced psoriasis-like lesions." (PMID 33214582, 2020). "In addition, signs of NETosis were visible in the psoriasis skin lesions in our LSCM experiments, while NET-related MPO–DNA complexes, correlating moderately with the PASI, were present in the blood of patients with psoriasis." (PMID 40270954, 2025). "The characterization and utilization of oxidative stress indicators, including MPO, PON, SIRT, SOD, and CAT provide novel understanding of the development of psoriasis." (PMID 39456475, 2024). "However, we observed a positive correlation of ULK1 with myeloperoxidase (MPO), a major protein constituent of granules, in neutrophils from both healthy donors and patients with psoriasis." (PMID 34421918, 2021). "The proteins identified in our previous study, including MPO, TYMP, IMPDH, ALDHs, and GSTT1, were also highly expressed in this study, which indicated that drug metabolism played an important role in the pathogenesis of psoriasis." (PMID 32817748, 2020). "MPO is involved in the respiratory burst and can bind to CD11b/CD18 integrins, thereby contributing to the upregulation and augmentation of neutrophil degranulation in psoriasis." (PMID 31649677, 2019). "Patients with psoriasis who were treated with etanercept showed decreased blood levels of cardiovascular biomarkers, such as soluble VCAM-1, soluble ICAM-1, soluble E-selectin, MMP-9, MPO, and tPAI-1." (PMID 29065479, 2017). "Moreover, the baseline MPO-DNA level and change in MPO-DNA during treatment were associated with skin condition improvement in the case of patients with PsA, but not with the PASI score in psoriasis." (PMID 39409000, 2024). "Some studies have shown decreased levels of IL-17A, TNF-α, S100A15, S100A7, S100A9 and IL-6 gene expression in PBMCs after NB-UVB treatment in patients with psoriasis whereas other pro-inflammatory mediators such as sVCAM-1, sICAM-1, sE-selectin, MMP-9, and MPO showed no significant reduction." (PMID 30865695, 2019).